CD4 (CD4 molecule)
Diseases named in the same sentence as CD4 in open-access papers (continued):
Sharing a sentence is not in itself a finding about the gene and the disease.
liver fibrosis (170 papers, 2010 to 2026). "Previous studies have demonstrated that PKCλ/ι deficiency in CD4+ T cells suppresses Th2/Th17 differentiation, ameliorating schistosomiasis-induced hepatic fibrosis and house dust mite (HDM)-driven allergic asthma." (PMID 41154658, 2025). "CD4+ counts, albumin, direct bilirubin, and indirect bilirubin were associated with liver fibrosis, probably due to sociodemographic factors such as social stratum, level of education, and late diagnosis of HCV." (PMID 39599839, 2024). "Previous studies have found that liver fibrosis was associated with lower CD4+ T cells, some HBV genotypes or HBV viral load." (PMID 38518655, 2024). "We showed that higher serum levels of high mobility group box 1 (HMGB1), a damage associated molecular protein which increases with cellular apoptosis, at the time of enrolment and lower CD4+ T cell nadir (%) was associated with liver fibrosis progression." (PMID 38518655, 2024). "We explored additional parameters for liver fibrosis, finding CD4+ levels of ≤191.5 cells/mm3 linked to significant or advanced fibrosis." (PMID 38787212, 2024). "Liver fibrosis caused significant elevation on the percentage of CD4+CD69+ and CD8+CD69+cells in comparison to naïve group in the spleen." (PMID 35307625, 2022). "In case of CD127, IL7 receptor alpha chain, liver fibrosis caused an elevation on the percentage of CD4+CD127+ and CD8+CD127+ T cells compared to the healthy group." (PMID 35307625, 2022). "It appears that the branch of CD4+T-lymphocytes, the Th17 population, seems to be involved in the inflammation process that guides liver fibrosis and underlining liver pathologies." (PMID 34211477, 2021). "The outcomes of these interactions can lead to disease progression (i.e., CD4+ T cell decline, immune activation, and/or increased hepatic fibrosis/cirrhosis) and to increased risk of transmission." (PMID 34960656, 2021). "Multivariate analysis considering HIV viral load, CD4 cell count, gender and age of participant’s, revealed that these factors were independently associated with the occurrence of hepatic fibrosis in the participants of this study." (PMID 33059627, 2020). "Here, we aim to characterize the association of hepatic fibrosis with both the phenotype and function of peripheral NK cells and their regulation by CD4+ T‐cells, in HIV/HCV‐coinfected individuals." (PMID 31536177, 2019). "Among the covariates, only CD4 count <350 cells/μl was significantly associated with advanced liver fibrosis (aOR, 2.2, 95% CI: 1.05–4.62, p = 0.04) in the fully adjusted model." (PMID 31246992, 2019). "Other studies have identified improvement of liver fibrosis during drug treatment, associated with better recovery of CD4 T cells during therapy and younger age." (PMID 29466439, 2018). "This study identified older age and low CD4+ T‐lymphocyte counts as being associated with liver fibrosis." (PMID 30394678, 2018). "The CD4+ cells are predominantly associated with the secretion of Th2 cytokines which contributes to the development of hepatic fibrosis." (PMID 25948238, 2015). "MPTF activity is also associated with advanced liver fibrosis and with CD4 + HLADR+ immune activation." (PMID 25884329, 2015). "Several lines of evidence indicate that HIV-induced CD4 depletion is independently associated with the severity of liver fibrosis in chronic HCV infection." (PMID 24865485, 2014). "HIV induced loss of CD4 T-cells plus an impaired CD4 T-cell activity appear to contribute to progression of liver fibrosis in patients co-infected with HIV and hepatitis C virus (HCV)." (PMID 24151495, 2013). "Some have found that lower CD4-cell counts or the CD4 nadir is associated with more severe liver fibrosis and liver outcomes, whereas others have found no such association." (PMID 23226258, 2012). "Similarly, hepatic fibrosis in the established mouse model of CCl4-induced liver fibrosis was associated with enrichment of intrahepatic α4β7+ CD4 and CD8 T cells." (PMID 38727292, 2024).
liver fibrosis (continued). "CD4+ counts, albumin, direct bilirubin, and indirect bilirubin were associated with liver fibrosis." (PMID 38787212, 2024). "Previous reports suggested low CD4 cell counts to be associated with liver fibrosis." (PMID 35207770, 2022). "Risk factors for liver fibrosis included a CD4 T cell count <200 cells/mm3 or <500 cells/mm3 for the APRI score, while both APRI and Fib-4 scores were associated with a lower level of cholesterol (possibly due to the development of liver disease) and non-adherence to ART." (PMID 35966860, 2022). "In addition, lower CD4 lymphocyte counts have been associated with progression of liver fibrosis during HIV/HBV coinfected patients." (PMID 31752284, 2019). "Interestingly, a gradient of reduced risk of liver fibrosis was observed with increased CD4 counts strata, in particular the lowest risk was observed for patients with CD4 counts higher than 350 cells/microliter." (PMID 26640953, 2015). "Besides, uncontrolled HIV replication and low CD4 counts are both associated with accelerated liver fibrosis progression in HIV/HCV coinfected patients." (PMID 26123260, 2015). "In the univariate logistic regression analyses, in addition to sCD14 and ALT, aspartate aminotransferase (AST) (P = 0.0009), platelet counts (P = 0.0055), and CD4 cell counts (P = 0.05) were associated with the stage of liver fibrosis and so were introduced into the model." (PMID 23527135, 2013). "In the multivariable analysis of HIV-infected participants adjusted for age, occupational fishing, positive HBsAg, gender, heavy liquor use, ART, and CD4 nadir, the associations between herb use and significant liver fibrosis were similar to findings among all participants." (PMID 23209545, 2012). "However, many of these studies found liver fibrosis to be associated with other factors during drug therapy, including poor viral control, low CD4 T cell counts, presence of HCV infection, older age, and alcohol abuse, which were not recapitulated in our SIV-macaque experiments." (PMID 29466439, 2018). "Interestingly, uncontrolled HIV replication and low CD4 counts are both associated with accelerated liver fibrosis progression in HIV/HCV coinfected patients, suggesting that earlier use of antiretroviral therapy could ameliorate this harmful effect." (PMID 26123260, 2015). "Additionally, low CD4 + cells counts are also associated with increased rates of liver fibrosis." (PMID 25066324, 2014). "On CD8+ T cells, the current study found that the probability of changes in expression of exhaustion markers on CD4+ T cells were less likely in patients with advanced liver fibrosis." (PMID 40959088, 2025). "To further investigate the role of PKCλ/ι in Schistosoma japonicum-induced hepatic fibrosis, we employed a CD4+ T-cell-specific PKCλ/ι conditional knockout (KOSJ) mouse model, with wild-type (WTSJ) mice used as controls." (PMID 41154658, 2025). "Overall, this study showed that FABP7 in hepatic macrophages regulated PPARγ expression and M2 polarization, thereby promoting liver fibrosis via fibroblast activation and CD4+ T-cell migration." (PMID 40017805, 2025). "This study established a correlation between liver fibrosis stage and CD4, and PD-1 expression: the more advanced fibrosis, the higher the frequency of CD4+PD-1+ T cells." (PMID 40959088, 2025). "Global CD4+ T cell responses overall show reduced exhaustion and activation over time, but the extent of the recovery appears limited in patients with advanced liver fibrosis." (PMID 40959088, 2025). "CD4+ and CD8+ T cells are vital in liver fibrosis, with CD8+ T cells causing liver damage and CD4+ T cell subsets shaping the immune response." (PMID 40362271, 2025). "In this study, we demonstrated that FABP7 in hepatic macrophages regulated M2 polarization and promoted liver fibrosis by activating fibroblasts and regulating CD4+ T-cell migration." (PMID 40017805, 2025).
liver fibrosis (continued). "When SCID mice with liver fibrosis induced by CCl4 or TAA were transferred with CD8+ T cells or CD4+ T cells, liver fibrosis was exacerbated through CD8+ T cell transfer, reflecting the contribution of CD8+ T cells to the pathogenesis of fibrosis." (PMID 40616144, 2025). "Differences in clinical and laboratory predictors of liver fibrosis progression were tested followed by regression analysis adjusted for CD4+ T-cells at study entry." (PMID 38518655, 2024). "Body mass index (OR = 1.08), serum lipid levels (OR = 0.96), viral load at diagnosis (OR = 1.00005), and low CD4+ cell count (OR = 0.977) were also correlated with liver fibrosis." (PMID 38930595, 2024). "Depletion of hepatic macrophages accelerated hydatid cyst establishment and growth by inhibiting CD4+ T-cell infiltration and liver fibrosis during E. granulosus s." (PMID 37930989, 2023). "We therefore performed immunofluorescent staining using CCR6 as marker for IL-17A–producing CD4+ T cells, and α-smooth muscle actin (αSMA) as marker for the cells potentially responsible for liver fibrosis." (PMID 36625344, 2023). "Pathologically, many CD4+T cells and lymphocytic inflammatory infiltrate accompany variable hepatocyte necrosis and subsequent hepatic fibrosis." (PMID 38111045, 2023). "establishment and growth partially by inhibiting liver fibrosis and CD4+ T-cell recruitment in the mouse model." (PMID 37930989, 2023). "It is shown that APRI properly grades liver fibrosis in mono- and co-infected patients with higher CD4+ counts, but only a low proportion of patients with low CD4+ count is clearly classified with this index." (PMID 37942194, 2023). "MSCs or MSC-conditioned medium (MSC-CM) treatment increased IL-10 and IDO levels in serum and ameliorated CCl4-induced liver fibrosis through downregulating IL-17 producing CD4+ T cells and upregulating IL-10 producing CD4+ T cells in the liver." (PMID 36248254, 2022). "CD4+ T cells activity mediates the progression of liver fibrosis by intrinsic apoptosis, by secreting signature cytokines IL-4, IL-10, and IFN-γ, and by stimulating other immune cells such as NK cells." (PMID 35903097, 2022). "The independent risk factors for significant liver fibrosis (≥F2) were HCV coinfection and time of exposure to efavirenz; CD4 cell count was a protective factor." (PMID 34064387, 2021). "The results showed that liver fibrosis caused a significant increase in the proportion of CD4+ IFN-γ+ T-cells (Th1), CD4+ IL-17A+ T-cells (Th17), and CD4+ CD25+ Foxp3+ Tregs, compared with the control group (p < 0.05)." (PMID 34158112, 2021). "Despite a lack of correlation between regulatory T cells and AST, ALT, or GGT, we observed a positive link between putative CD4+CD25+CD127− regulatory cells and the parameter associated with hepatic fibrosis—APRI." (PMID 34452314, 2021). "Humanized mice on high fat diet with induced NAFLD develop liver fibrosis that is mediated by CD4+IL17A+ cells." (PMID 34211477, 2021). "CD4+ T cells are considered to be vital in chronic liver diseases, but their exact roles in hepatic capillarization, the typical characteristic of liver fibrosis, are poorly understood." (PMID 33535174, 2021). "Significant liver fibrosis (p < 0.05) was associated with HCV coinfection (OR 3.4; 95% CI, 1.1–10.6), total CD4 (OR 0.99; 95% CI, 0.99–1), and time of efavirenz exposure (OR 1.2; 95% CI, 1.0–1.3)." (PMID 34064387, 2021). "We isolated splenocytes from control and liver fibrosis (LF) model mice to induce the differentiation of CD4+ T cell subsets by Cell Stimulation Cocktail ex vivo." (PMID 34158112, 2021). "This study aimed to assess the roles of typical subtype of CD4+ T cells, named T helper 1 (Th1) and Th2 cells in liver fibrosis." (PMID 33535174, 2021).
liver fibrosis (continued). "In a coculture system, it was found that CD8+ and CD4+T cells of peripheral blood lymphocytes (PBLs) isolated from hepatitis B/hepatitis C patients accompanied with hepatic fibrosis are activated by adhering to HSCs and being phagocytosed." (PMID 32454856, 2020). "A marked egg-induced CD4+ T cell programmed inflammation and subsequent hepatic fibrosis characterize the pathogenesis of schistosomiasis." (PMID 32503644, 2020). "Pretreatment exhaustion markers expression correlated with liver fibrosis score: the more advanced fibrosis, the higher percentage of CD4+PD-1+ T-cells (median 20.1% (range 7.0–52.7%) in F0/1 vs 25.4% (8.8–43.8%) in F2 vs 26.8% (15.0–38.4%) in F3, P = 0.0125)." (PMID 32994477, 2020). "In liver fibrosis caused by CCl4, the change trend of CD3+, CD4+ T cells was similar to that in mice infected by S. japonicum." (PMID 33117360, 2020). "Liver injury gives rise to CD8 T cell infiltration and activation; therefore, inactivating CD4 T cells leads to liver fibrosis." (PMID 33391261, 2020). "In mansonian schistosomiasis, hepatic fibrosis is initiated by vigorous granulomatous responses to tissue-entrapped parasite eggs that is mainly orchestrated by cross-regulatory CD4+ T cell." (PMID 31950032, 2019). "It has been reported that HIV/HCV‐coinfected subjects with higher chances to develop liver fibrosis are those with lower CD4+ T‐cell recovery after HIV treatment." (PMID 31536177, 2019). "It would be very interesting to investigate the potential role of HIV‐ or HCV‐specific CD4+ T‐cells to modulate liver fibrosis." (PMID 31536177, 2019). "HIV-HBV co-infected patients have higher mortality, more advanced CD4 T cell depletion, and liver fibrosis that improves in conjunction with ARV therapy." (PMID 31752729, 2019). "In analyses using log‐transformed values and adjusting for age, race, liver fibrosis stage, drug and alcohol use, CD4 and viral suppression status, the decrease in sCD163 and sCD14 remained significant." (PMID 31339004, 2019). "HIV-HBV co-infected participants had lower CD4 T cell counts at baseline and higher levels of hepatic fibrosis scores compared to HIV-infected patients." (PMID 31752729, 2019). "In unadjusted analyses, the proportions of senescent, memory and naïve CD8+ and CD4+ T-cells were similar by liver fibrosis category (p > 0.05)." (PMID 31892306, 2019). "In the analysis of peripheral blood, CD4+ T cell phenotypes observed a low frequency of these cells in patients with advanced liver fibrosis (F3-4)." (PMID 31780860, 2019). "The higher frequency of AE did not correlate with hemoglobin, transaminases, total bilirubin, albumin, platelet count, CD4 count, cure rates, or degree of liver fibrosis." (PMID 29921760, 2018). "Further findings suggest that HIV directly interacts with hepatocytes, Kupffer cells and hepatic stellate cells, apart from indirectly affecting liver fibrosis through systemic immune activation with inflammation and reduced CD4 T-cell counts." (PMID 29346443, 2018). "Since CRF14_BG induced a massive depletion of CD4 T cells it was expected to be associated with impaired HCV immune control and thus higher replication and hepatic fibrosis." (PMID 29016621, 2017). "Those who died were more likely to use cocaine (HR=3.8, P=0.006) and have more advanced liver fibrosis (HR=1.34, P<0.0001), adjusting for age, gender, CD4 cell count and HIV-viral load at baseline and over time." (PMID 28540368, 2016). "The variables for adjustment were age, HIV transmission category, liver fibrosis, baseline CD4+ T-cell counts, antiretroviral therapy, and sustained virologic response (SVR)." (PMID 26849641, 2016). "CD4+ IL-17-secreting T cells have been shown to contribute to pathology in some models of liver fibrosis." (PMID 25590646, 2015). "A potential mechanism by which reduced CD4 cell counts promote hepatic fibrosis is a reduction in the secretion of T-helper (Th) 1 cytokine IFN-γ, a well-known anti-fibrotic cytokine." (PMID 24865485, 2014).
liver fibrosis (continued). "Next, we investigated the correlation between activation status of CD4 T cells and liver fibrosis before and after IFN-α therapy." (PMID 25007250, 2014). "CD127 expression on CD4 T cells also correlated inversely with liver fibrosis (despite reduction of APRI score in SVRs after IFN-α therapy)." (PMID 25007250, 2014). "Our data indicate that age, gender, a diagnosis of advanced liver fibrosis, CD4+ cell count and successful HIV therapy, leading to undetectable plasma virema, failed to exhibit significant effects on HCV RNA levels." (PMID 25104966, 2014). "Interestingly, we also found that higher CD4 counts were associated with a reduced risk of substantial increases in HA levels during follow-up, consistent with the assumed protective role of high CD4 counts on the risk of progression of liver fibrosis in co-infected patients." (PMID 23724041, 2013). "Significant decrease of CD4 cell number in patients with advanced liver fibrosis were also detected (432 vs. 232 cells/mm3; P = 0.004)." (PMID 23613686, 2013). "Covariates: alcohol, liver fibrosis, comorbidities, CD4 count, antiretroviral therapy, substance use." (PMID 23987993, 2013). "To obtain in vivo evidence about effect of Treg/Th17 balance in liver fibrosis, we established ConA-induced mouse liver fibrosis models, characterized by the infiltration of abundant CD4+ cells to induce immune-mediated liver fibrosis." (PMID 22745730, 2012). "Importantly, autophagy impairment in CD4 T cells is also observed in patients with advanced liver fibrosis, and restoration of autophagy decreases the frequency of pathogenic Th17 cells and attenuates fibrosis." (PMID 41487942, 2026). "Moreover, the low prevalence of advanced liver fibrosis is probably a reflection of the relatively young age of the participants in the cohort and the relatively conserved number of CD4 cell counts." (PMID 40004700, 2025). "HIV viremia accelerates the progression of liver fibrosis to cirrhosis or may directly promote the development of hepatocarcinogenesis through oxidative stress, immune dysregulation, and a reduction in CD4+ cells, which leads to microbial translocation." (PMID 41471957, 2025). "For instance, miR-21 promotes CD4+ T cell glycolysis through the PTEN/PI3K/AKT pathway, which increases the cell cycle, promotes CD4+ T cell polarization toward the Th2 phenotype, and releases the fibrogenic cytokine IL-13, which is involved in arsenite-induced hepatic fibrosis." (PMID 40122853, 2025). "In this study, we found that FABP7-deficient macrophages exhibited impaired M2 polarization, which reduced the fibrotic response of myofibroblasts and CD4+ T-cell infiltration into the liver tissues in a carbon tetrachloride (CCl4)-induced hepatic fibrosis model." (PMID 40017805, 2025). "In studies focused on the roles of absolute CD4+ cell counts and CD4% in clinical decision‐making for HIV, there is evidence that liver fibrosis and/or cirrhosis may play a role in lower absolute CD4+ cell counts and discordance with CD4%." (PMID 39656170, 2025). "CD4 deletion attenuates steatohepatitis and liver fibrosis in a murine MASH model." (PMID 40631180, 2025). "The distribution and number of CD4+ T cells in the peripheral blood correlated with accumulation of G-MDSCs, which might closely relate to impairment of host immune function and liver fibrosis." (PMID 39212529, 2024). "Decline in the CD4+ counts directly affects the strength of APRI in classifying liver fibrosis." (PMID 37942194, 2023). "larval establishment and growth partially by inhibiting CD4+ T-cell recruitment and liver fibrosis." (PMID 37930989, 2023). "establishment and growth partially by inhibiting liver fibrosis and CD4+ T-cell recruitment." (PMID 37930989, 2023). "At the final visit, non-adherence to ART and CD4+T cell counts remained associated with liver fibrosis." (PMID 35966860, 2022).